IL17B (interleukin 17B)
Diseases named in the same sentence as IL17B in open-access papers (continued):
Sharing a sentence is not in itself a finding about the gene and the disease.
lung carcinoma (5 papers, 2021 to 2023). "A previous study also reported that IL-17B treatment caused significant IL-17RB upregulation in lung cancer cells." (PMID 33649532, 2021). "Despite the potential role of the IL-17B/ILRB trial in lung cancer, microarray dataset analysis in a study was linked to IL-17B and IL-17RB gene expression indicating least patient survival." (PMID 34336101, 2021). "Besides, this finding linked the role of IL-17B with poor prognosis in lung cancer patients among many other types, identifying clinical relevance." (PMID 34336101, 2021).
breast tumor (4 papers, 2015 to 2021). "Although they share the IL-17RB chain as co receptor, pro-oncogenic features were described for the breast tumor cell secreted IL-17B, whereas tumor suppressor role was associated to the normal breast epithelial cells secreted IL-17E." (PMID 26154409, 2015). "Similary, the IL17B/IL17RB pathway promotes resistance to paclitaxel in breast tumors via the ERK1/2 pathway." (PMID 34724890, 2021). "In vivo, IL-17B induced resistance to paclitaxel and treatment with an anti-IL-17RB neutralizing antibody completely restored breast tumor chemosensitivity, leading to tumor shrinkage." (PMID 29371916, 2017). "Recent works focused on IL-17B and IL-17E, which are found in breast tumor microenvironment, have reported opposite functions." (PMID 26154409, 2015). "Furthermore, IL-17E (IL-25) markedly reduces growth of MDA-MB468 breast tumor xenografts in vivo, while IL-17B increases it." (PMID 32373132, 2020). "We next investigated whether activation of the IL-17B/IL-17RB pathway was involved in the development of resistance to conventional chemotherapeutic agents, such as paclitaxel, in breast tumors." (PMID 29371916, 2017). "Interestingly, in contrast to IL-17A, which is produced by TILs, the main source of IL-17B in breast tumors seems to be tumor cells themselves and potentially fibroblasts, but not TILs." (PMID 29371916, 2017). "As IL-17B role in the response to anti-cancer therapies has not been precisely investigated yet, we decided to explore IL-17B function in breast tumor response to chemotherapy." (PMID 29371916, 2017).
asthma (3 papers, 2021 to 2022). "Thus, we speculate that IL-17A and IL-17B interact with various immune factors, specifically TGF-β1, to contribute severity of asthma." (PMID 34221020, 2021).
colon carcinoma (3 papers, 2018 to 2026). "In moderately and poorly differentiated colon cancer cells, IL-17B tissue expression is elevated, and the number of IL-17B+ stromal cells in colorectal cancer was significantly higher than in the control group." (PMID 40536951, 2026). "In a separate set of experiments, we also tested goat anti-IL-17B (AF1248) Abs that, in recent publications, have been shown to positively stain, by IHC and IF, neutrophils present in tissue samples from RA and colon carcinoma (CCR) patients." (PMID 29719541, 2018).
melanoma (3 papers, 2017 to 2022). A malignant, usually aggressive tumor composed of atypical, neoplastic melanocytes. "SNP variants in Ebf1 were likewise associated with IL-12 p40 blood levels in humans with Stage I melanoma, and SNP in both IL17B and Ebf1 were associated with melanoma susceptibility and patient outcomes." (PMID 35591856, 2022). "The melanoma EV-induced up-regulation of ghrelin, a 28-residue peptide hormone that accelerates the growth of MSCs and has an anti-inflammatory activity, is consistent with the down-regulation of IL-26, IL-17B, caspase-1 and CCL5." (PMID 28129640, 2017). "Among melanoma, a lower CTL level indicates better patient survival, but only when IL-17B or IL-17F has a high expression level (p < 0.05)." (PMID 36159856, 2022).
thyroid cancer (3 papers, 2019 to 2021). "Studies have reported that IL-17B enhances invasion and metastasis in lung and thyroid cancer." (PMID 33649532, 2021). "Indeed, in the SW1736 thyroid cancer cell line, IL-17B-dependent stimulation of IL-17RB induces ERK1/2 activation and increases expression of the matrix metalloproteinase MMP-9 expression, a key mediator of tumor invasion and metastasis formation." (PMID 32373132, 2020).
autoimmune disease (2 papers, 2010 to 2021). A disorder resulting from loss of function or tissue destruction of an organ or multiple organs, arising from humoral or cellular immune responses of the individual to their own tissue constituents. "IL-17B is a member of the IL-17 cytokine family which have been implicated in inflammatory response and autoimmune diseases such as rheumatoid arthritis." (PMID 20467469, 2010). "Elevated levels of IL-17B expression have been found in synovial tissue of CIA mice and RA patients while further blockade of IL-17B with neutralizing antibodies ameliorates disease progression, indicating a pathogenic role of IL-17B in autoimmune diseases." (PMID 34122457, 2021).
COVID-19 (2 papers, 2023 to 2024). A disease caused by infection with severe acute respiratory syndrome coronavirus 2. "Another GWAS study in Thai suggested a protective effect of IL17B on 5q32 against disease, and a recent release from IHG showed that MUC5B and ELF5 on chr11 might be associated with immune system regulation in the lungs in the development of COVID-19." (PMID 36649279, 2023).
gastric tumor (2 papers, 2016 to 2025). "Interestingly, the expression of IL-17B was upregulated in patient serum rather than gastric tumor tissues." (PMID 27146881, 2016).
glioblastoma (2 papers, 2015 to 2023). The most malignant astrocytic tumor (WHO grade IV). "We identified a six gene cytokine-related signature (CCL2, CCR2, CXCL10, IL10RB, IL17B, and IL17R) capable of dividing glioblastoma patients into a low risk score group with favorable survival and a high risk score group with poor survival." (PMID 25978454, 2015).
leukemia (2 papers, 2020 to 2025). A malignant (clonal) hematologic disorder, involving hematopoietic stem cells and characterized by the presence of primitive or atypical myeloid or lymphoid cells in the bone marrow and the blood. "Interestingly, IL-17RB knockdown in MOLM-13 AML cells had a stronger effect than IL-17B knockdown in vivo, reflecting the potential contribution of the microenvironment-derived IL-17B to the signal delivered to IL-17RB-positive leukemia cells." (PMID 32373132, 2020).
Obesity (2 papers, 2017 to 2022). Accumulation of substantial excess body fat. "If identified, this could drive a therapeutic strategy for white matter repair by targeting the source of IL-17B in obesity." (PMID 36543124, 2022). "This miRNA has not been previously reported as associated with obesity, however among its targets are those involved in the pathogenesis of obesity-related complications, e.g., genes encoding interleukins (IL-6, IL-17B and IL-22), apolipoproteins (APOA5) and their receptors (APOBR)." (PMID 29280944, 2017).
rheumatoid arthritis (2 papers, 2010 to 2021). A chronic, systemic autoimmune disorder characterized by inflammation in the synovial membranes and articular surfaces. "Elevated IL-17B levels have been reported in the synovial tissues of rheumatoid arthritis patients, which can promote TNF-α-induced G-CSF and IL-6 expression in fibroblasts." (PMID 33545363, 2021).
systemic sclerosis (2 papers, 2023 to 2024). A chronic disorder, possibly autoimmune, marked by excessive production of collagen which results in hardening and thickening of body tissues. "Many studies have reported that IL-17B is pathogenic in inflammatory arthritis and gastroenterology cancers, and the expression levels of IL-17B are significantly higher in patients of systemic sclerosis than in controls." (PMID 38045694, 2023). "However, serum levels of IL-17B and IL-17E are elevated in patients with systemic sclerosis compared to controls." (PMID 39502194, 2024).
acute myeloid leukemia (1 paper, 2020). Acute myeloid leukemia (AML) is a group of neoplasms arising from precursor cells committed to the myeloid cell-line differentiation. "Additionally, mRNA expression profiles analysis in the HemaExplorer database showed that IL-17B and IL-17RB are strongly expressed in acute myeloid leukemia (AML), compared with normal hematopoietic stem cells." (PMID 32373132, 2020).
aortitis (1 paper, 2019). Inflammation of the aorta. "Therefore, IL-17B may have a compensatory role in induction of type 3 immune responses in the aortitis of Il25−/−Il1rn−/− mice." (PMID 31745167, 2019).
Arthritis (1 paper, 2015). Inflammation of a joint. "For instance, IL-17B was observed to participate in a murine model of collagen-induced arthritis whereas treatment with IL-17B neutralizing antibody can successfully suppress arthritis." (PMID 26146463, 2015).
atherosclerosis (1 paper, 2022). A disease characterized by the build-up of fatty material and calcium deposition in the arterial wall resulting in partial or complete occlusion of the arterial lumen. "The transcript levels of other two IL-17 subtypes, IL-17B and IL-17D, are reduced in psoriatic lesions, but the effects of IL-17B and IL-17D in atherosclerosis are unknown." (PMID 35514987, 2022).
Autoimmunity (1 paper, 2022). The occurrence of an immune reaction against the organism's own cells or tissues. "The up- or down-regulation of IL-17 genes (IL-17A, IL-17B, IL-17D, and IL-17F) resulted in decreased expression of many cytokines and chemokines, which are associated with autoimmunity and immune cell functions." (PMID 35466218, 2022).
cerebral small vessel disease (1 paper, 2022). Cerebral small vessel disease is the term currently used to pathological processes that affect the brain parenchymal circulation (arterioles, capillaries, and veins). "In this cohort, the burden of pre-existing cerebral small vessel disease indicated by modified Fazekas scale scoring of white matter hyperintensities is significantly different in IL-17B+ subjects compared with IL-17B− subjects (p < 0.0001)." (PMID 36543124, 2022). "With a working model suggesting that DIO drives white matter endothelial CXCL5 expression through IL-17B/IL-17Rb signaling, we sought to establish the relevance of this signaling cascade to human cerebral small vessel disease and vascular cognitive impairment." (PMID 36543124, 2022).
demyelinating disease (1 paper, 2022). A broad group of disorders that affect the myelin sheaths that cover the neurons. "IL17B (down regulated) protein is localised to neuronal cell bodies and is linked to Charcot–Marie–Tooth (CMT) demyelinating disease." (PMID 35692428, 2022).
depression (1 paper, 2020). "IL-17, a pro-inflammatory cytokine, is a member of the cytokine family comprising IL-17A, IL-17B, IL-17C, IL-17D, IL-17E (IL-25) and IL-17F and it was found before, to be elevated in the serum of patients suffering from depression." (PMID 33322667, 2020).
diabetes (1 paper, 2012). "Conversely, 9130005N14R, Thsd4 (thrombospondin type 1 domain containing 4), and Il17b (interleukin 17B) were also responsive to diet only under conditions of hyperglycemia, but then responded to diabetes when breeder diet was consumed." (PMID 22701643, 2012).
Erythema (1 paper, 2019). Redness of the skin, caused by hyperemia of the capillaries in the lower layers of the skin. "In BP, BPDAI subscore analysis showed that IL-17B was negatively correlated with the skin blisters/erosions lesions but not with the erythema/urticaria lesions." (PMID 31572359, 2019).
Fever (1 paper, 2022). Body temperature elevated above the normal range. "The interleukin cytokines IL6, IL27, and IL17B, were upregulated in the medium and high dose groups resulting in hemorrhagic fever by cytokine storm." (PMID 35854219, 2022).
fungal infections (1 paper, 2024). "The IL‐17 family of cytokines consists of six groups: IL‐17A, IL‐17B, IL‐17C, IL‐17D, IL‐17E and IL17‐F, which are involved in the development of autoimmunity, inflammation, tumours, host defences against bacterial and fungal infections, and mucosal host defence mechanisms." (PMID 38363001, 2024).
immune deficiency (1 paper, 2007). "For example, the increased expression of IL-17B in neonatal monocytes is consistent with the observations of Vanden Eijnden and colleagues that newborns compensate for their relative immune deficiency by over-expression of the IL23-IL-17 signalling pathway in dendritic cells." (PMID 17306030, 2007).
invasive mammary carcinoma (1 paper, 2022). "IL17B levels were significantly higher in our DCIS and invasive mammary carcinoma patients and diminished in benign and control groups." (PMID 34997107, 2022).
malaria (1 paper, 2024). Malaria is a serious and sometimes fatal disease caused by a parasite that commonly infects a certain type of mosquito which feeds on humans. "In our study, IL17B is upregulated during the recovery phase of malaria and, therefore, might possess a defensive role." (PMID 37831367, 2024).
oral cancer (1 paper, 2022). "A recent study also highlighted that the salivary levels of interleukin 17A (IL-17), interleukin 17B (IL-17B), and TNF-α were strictly related to oral cancer progression." (PMID 36005828, 2022).
periodontitis (1 paper, 2023). An acute or chronic inflammatory process that affects the tissues that surround and support the teeth. "In the first step of our study, we compared the expression of IL-17A and IL-17B at the mRNA level in gingival tissue in patients with periodontitis and control subjects." (PMID 37510729, 2023). "We have shown lower expression of IL-17B at the mRNA level in patients with periodontitis in comparison with healthy subjects." (PMID 37510729, 2023). "The expression of IL-17B mRNA was statistically significantly lower in patients with periodontitis in comparison with healthy subjects (p < 0.048)." (PMID 37510729, 2023). "The expression of IL-17B was statistically significantly lower in patients with periodontitis in comparison with healthy subjects (median: 0.00017, Q1–Q3: 0.000087–0.0021 vs. median: 0.0042, Q1–Q3: 0.00076–0.012, respectively, p = 0.048)." (PMID 37510729, 2023). "In our study, we examined the expression of IL-17A and IL-17B at the mRNA level, as well as IL-17 protein expression in gingival tissue from patients with periodontitis as well as in healthy subjects." (PMID 37510729, 2023). "The aim of this study was to examine the expression and localization in gingival tissue of IL-17A and IL-17B in patients with periodontitis." (PMID 37510729, 2023). "The results of previous studies suggest that IL-17A and IL-17B isoforms may play the most important role in the development of periodontitis." (PMID 37510729, 2023). "It is possible that IL-17B expression at the mRNA level in gingival tissue may be inhibited by other mediators involved in the development of periodontitis." (PMID 37510729, 2023).
pneumonia (1 paper, 2024). An acute, acute and chronic, or chronic inflammation focally or diffusely affecting the lung parenchyma, caused by an infection in one or both of the lungs (by bacteria, viruses, fungi, or mycoplasma.). "When dysregulated, lung commensal bacteria such as Bacteroides and Prevotella can provoke macrophages to produce IL17B via toll-like receptor (TLR)–Myd88 signaling, accelerating pneumonia and fibrosis as a result." (PMID 39010112, 2024).
Sepsis (1 paper, 2023). Sepsis is defined as life-threatening organ dysfunction caused by a dysregulated host response to infection. "Moreover, IL17B can inhibit LPS-induced inflammation in BMDM and in vivo sepsis model." (PMID 36814913, 2023).
Stroke (1 paper, 2022). Sudden impairment of blood flow to a part of the brain due to occlusion or rupture of an artery to the brain. "Using available plasma samples from a single-center cohort study including subjects presenting with acute neurologic symptoms suggestive of stroke, we assayed plasma levels of IL-17B and CXCL5 using a custom Luminex assay." (PMID 36543124, 2022).
systemic lupus erythematosus (1 paper, 2024). An autoimmune multi-organ disease typically associated with vasculopathy and autoantibody production. "Intriguingly, IL-17B deficiency aggravated disease in lupus-prone mice and promoted the activation of B cells and the differentiation of germinal center B cells and plasma cells, while recombinant mouse IL-17B (rmIL-17B) significantly alleviated disease in lupus-prone mice." (PMID 39115936, 2024).
tendinopathy (1 paper, 2025). "Future work may nevertheless investigate other IL-17 family members, for example, IL-17B in late-stage tendinopathy." (PMID 39988349, 2025). "In addition, here, we demonstrate the differential expression of IL17A in contrast to the other IL-17 family members, IL17B, IL17C, IL17D and IL17E in early-stage tendinopathy compared with late-stage tendinopathy and healthy tendon." (PMID 39988349, 2025).
thrombosis (1 paper, 2022). "The KEGG enrichment analyses indicated that the highly expressed IL-17B in the vascular wall during thrombosis was significantly associated with the RIP3/MLKL signaling pathway." (PMID 36046722, 2022). "Therefore, the prevention of vascular endothelial necroptosis might be an effective treatment to reduce thrombosis-associated injury, and IL-17B might be a promising therapeutic target for the protection of vascular endothelial cells during DVT." (PMID 36046722, 2022). "Compared with the DVT group, the weight of the thrombosis in DVT/IL-17B was increased (P < 0.05), and so was the cross-sectional area of the thrombus (P < 0.05)." (PMID 36046722, 2022). "We explored the role of IL-17B in vascular endothelial necroptosis during DVT, with the ultimate goal of understanding their roles in regulating thrombosis." (PMID 36046722, 2022). "This study investigated whether vascular endothelial necroptosis is involved in deep vein thrombosis (DVT) and how IL-17B facilitates necroptosis signaling." (PMID 36046722, 2022). "Similarly, in vivo, the plasma IL-17B, IL-6, and TNF-α were significantly increased after thrombosis in WT mice, and the plasma IL-6 and TNF-α was increased more significantly after the intervention of IL-17B protein on the basis of ligation of IVC (all P < 0.05)." (PMID 36046722, 2022). "Therefore, the aim of this study was to examine the effects of RIP3, MLKL, and IL-17B on cell viability in vitro and to examine the role of IL-17B in regulating RIP3 and MLKL in the vascular wall, thus modulating thrombosis, in a DVT mouse model." (PMID 36046722, 2022). "All these findings indicated that vascular endothelial necroptosis is involved in DVT and that IL-17B could facilitate necroptosis signaling, thus promoting thrombosis, but this is not the only pathway through which IL-17B plays a role in DVT." (PMID 36046722, 2022).
viral infections (1 paper, 2020). "However, little is known about the role of IL-17B in the control of viral infections." (PMID 32517220, 2020).